ZBTB8OSP2 (zinc finger and BTB domain containing 8 opposite strand pseudogene 2)
Gene: Processed pseudogene on chromosome 2 (231,433,923 to 231,434,426, reverse strand). Ensembl gene ENSG00000172799.
Diseases named in the same sentence as ZBTB8OSP2 in open-access papers:
ZBTB8OSP2 is named in the same sentence as 1 disease in open-access papers, as found by Europe PMC text mining. Sharing a sentence is not in itself a finding about the gene and the disease. The quoted sentences say what the papers report.
eating disorder (1 paper, 2022). A broad group of psychological disorders with abnormal eating behaviors leading to physiological effects from overeating or insufficient food intake. "The following predicted gene, named ZBTB8OSP2 (729898), is a pseudogene and has been reported to contribute to anti-saccade response and eating disorders." (PMID 35721855, 2022).